TMEM86A (transmembrane protein 86A)
Description:
Catalyzes the hydrolysis of the vinyl ether bond of choline or ethanolamine lysoplasmalogens, forming fatty aldehyde and glycerophosphocholine or glycerophosphoethanolamine, respectively and is specific for the sn-2-deacylated (lyso) form of plasmalogen. Plays an important role in lysoplasmalogen metabolism in the adipocyte tissue and macrophages.
Synonyms: FLJ90119
Tractability: Antibody: UniProt predicts a signal peptide or a membrane-spanning region.
Gene: Protein-coding gene on chromosome 11 (18,693,122 to 18,704,785, forward strand). Ensembl gene ENSG00000151117.
Subcellular location: Endoplasmic reticulum membrane
Subcellular location (Human Protein Atlas): Golgi apparatus; Nucleoplasm
Gene Ontology:
Molecular function: alkenylglycerophosphocholine hydrolase activity; protein binding; hydrolase activity
Cellular component: endoplasmic reticulum membrane; membrane
Genetic constraint (gnomAD): Loss-of-function variants: 13 observed, 20.15 expected, observed/expected ratio (o/e) 0.65, 90% interval 0.42 to 1.03. The upper end of that interval is the gene's LOEUF score, 1.03, which puts it in group 4 of 6, group 1 being the genes least tolerant of losing a copy. Missense variants: 238 observed, 311.83 expected, observed/expected ratio (o/e) 0.76, 90% interval 0.69 to 0.85. Synonymous variants: 125 observed, 134.03 expected, observed/expected ratio (o/e) 0.93, 90% interval 0.81 to 1.08.
Homologues: Orthologues: chimpanzee TMEM86A (99% identical), macaque TMEM86A (98% identical), rabbit TMEM86A (92% identical), pig TMEM86A (90% identical), dog TMEM86A (90% identical), guinea pig TMEM86A (90% identical), mouse Tmem86a (89% identical), rat Tmem86a (86% identical), zebrafish tmem86a (71% identical), Drosophila melanogaster CG7582 (33% identical). Paralogues in human: TMEM86B (34% identical).
Diseases named in the same sentence as TMEM86A in open-access papers:
TMEM86A is named in the same sentence as 7 diseases in open-access papers, as found by Europe PMC text mining. Sharing a sentence is not in itself a finding about the gene and the disease. The quoted sentences say what the papers report.
Obesity (2 papers, 2022 to 2023). Accumulation of substantial excess body fat. "In summary, our data suggest the important role of TMEM86A-mediated lysoplasmalogen metabolism in adipose tissue function and indicate a potential therapeutic strategy for obesity-related metabolic diseases." (PMID 35835749, 2022). "In the current study, we found that deletion of TMEM86A in adipocytes protects mice from obesity and insulin resistance in vivo." (PMID 35835749, 2022). "LPE P-18:0 levels are significantly lower in adipose tissue of human patients with obesity, suggesting that TMEM86A inhibition or lysoplasmalogen supplementation might be therapeutic approaches for preventing or treating obesity-related metabolic diseases." (PMID 35835749, 2022). "Collectively, these results indicate that lysoplasmalogens are key regulators of catabolic signalling in adipocytes, and suggest that TMEM86A might be targeted for obesity-related metabolic disease." (PMID 35835749, 2022). "Next, we examined whether the deletion of TMEM86A protects mice from obesity-induced metabolic dysfunction." (PMID 35835749, 2022). "Transcriptome-profiling (GEO: GSE94753) also shows that TMEM86A expression is upregulated in abdominal subcutaneous WAT from female patients with obesity compared to individuals without obesity." (PMID 37680891, 2023). "Furthermore, publicly available transcriptome-profiling (GEO: GSE94753) indicates that TMEM86A expression is upregulated in abdominal subcutaneous WAT from female patients with obesity manifesting insulin resistance (OIR) compared to individuals without obesity (NO)." (PMID 35835749, 2022).
metabolic disease (1 paper, 2022). A congenital disorder (due to inherited enzyme abnormality) or acquired (due to failure of a metabolically important organ) disorder resulting from an abnormal metabolic process. "Here the authors characterize the role of adipocyte TMEM86A as a lysoplasmalogenase and show its deletion is protective against high fat diet induced metabolic disease, an effect that can be recapitulated by plasmenyl lysophosphatidylethanolamine 18:0 supplementation." (PMID 35835749, 2022).
TMEM86A also shares sentences with these, for which no sentence is quoted: cancer (2 papers); bacterial infections (1); breast carcinoma (1); Insulin resistance (1); severe acute respiratory syndrome coronavirus 2 (1).